CENPF (centromere protein F)
Diseases named in the same sentence as CENPF in open-access papers (continued):
Sharing a sentence is not in itself a finding about the gene and the disease.
prostate carcinoma (48 papers, 2013 to 2025). A carcinoma that arises from epithelial cells of the prostate gland. "The differentially expressed analysis revealed that CENPF is the significantly higher expression in prostate cancer patients, and is associated with the poor progress-free interval of prostate cancer patients." (PMID 36937411, 2023). "Recently, TOP2A, MELK, and CENPF were also reported to be putative targets of miR-27a-5p and have been implicated in prostate cancer progression." (PMID 29415999, 2018). "The overexpression of FOXM1 and CENPF in prostate cancer have been linked to the loss of microRNAs such as miR-101 and miR-27a, to the synergistic cancer induction through the upregulation of PI3K and MAPK signaling pathways, and to the poor prognosis prediction of cancer patients." (PMID 36661515, 2023). "CENPF encodes a protein associated with the G2 phase, cell growth, protein synthesis, and the centromere–kinetochore complex and chromosomal segregation, and is related to aggressive prostate cancer." (PMID 36834602, 2023). "Indeed, CENPF was mechanically linked to altered metabolism and progression in prostate cancer, and may be a crucial regulator." (PMID 32040444, 2020). "The survival analysis revealed that progress-free interval is closely associated with the expression level of CENPF, TOP2A, and OR51E2 in the prostate cancer cohort." (PMID 36937411, 2023). "The boxplot demonstrated that SLPI is down-regulated in prostate cancer patients, while the CENPF, TOP2A and OR51E2 are up-regulated in prostate cancer patients compared with the normal cohort." (PMID 36937411, 2023). "As one of the biomarkers for CAFs, CENPF can promote the proliferation ability of prostate cancer cells." (PMID 36937411, 2023). "CRISPR-Cas9 silencing of CENPF in human prostate cancer cells resulted in decreased cell proliferation." (PMID 35884586, 2022). "For example, the overexpression of FOXM1 synergistically with CENPF in prostate cancer leads to the activation of PI3K and MAPK signaling pathways, which are key signaling pathways involved in prostate cancer malignancy." (PMID 35392496, 2022). "In prostate cancer, CENPF has been proved to be a primary regulatory factor of prostate cancer and a bleak prognostic predictor of survival and metastasis." (PMID 35123514, 2022). "CENPF, a master regulator of metastasis in prostate cancer, is inhibited by microRNA miR-101 and miR-27a." (PMID 35028418, 2022). "Studies have shown that CENPF has been up-regulated in a variety of malignancies, including nasopharyngeal carcinoma, esophageal squamous cell carcinoma and prostate cancer." (PMID 33428600, 2021). "Further studies have shown that COUP transcription factor 2 promoted prostate cancer metastasis through CENPF signal transduction." (PMID 33854594, 2021). "The stem cell marker, ASPM, promotes cell proliferation in prostate cancer 30 through the Wnt signaling pathway 28, and CENPF is involved in the formation of the centromere-kinetochore complex and was correlated with poor prognosis in the PDAC cohort of TCGA." (PMID 34326696, 2021). "Other studies showed that forkhead box M1 (FOXM1) and CENPF synergistically promoted malignant progression and poor prognosis of prostate cancer." (PMID 33428600, 2021). "Most importantly, FOXM1, at high expression levels, is known to act as a driver of prostate cancer malignancies by synergistically interacting with CENPF." (PMID 32629770, 2020). "CENPA expression tracks tightly with a number of previously identified prostate cancer pathogenesis factors including CENPF, UBE2C, and EZH2 (and Data Set S1)." (PMID 32371391, 2020). "CENPF is frequently overexpressed in pancreatic cancer, hepatocellular carcinoma, prostate cancer, and metastatic prostate cancer." (PMID 31527303, 2019). "CENPF has been shown to be a synergistic master regulator of prostate cancer malignancy and a prognostic indicator of poor survival and metastasis." (PMID 31632198, 2019).
prostate carcinoma (continued). "CENPF was found to be frequently upregulated in BC and other cancers prone to bone metastasis including lung cancer and prostate cancer." (PMID 31632198, 2019). "Previous studies have demonstrated that the overexpression of CENPF plays an important role in prostate cancer development." (PMID 31632198, 2019). "Here, the author show that that loss of miR-101 and miR-27a in prostate cancer cells can lead to COUP-TFII expression which in turn directly regulates FOXM1 and CENPF favouring prostate cancer metastasis." (PMID 27108958, 2016). "Identification of FOXM1 and CENPF as synergistic master regulators in aggressive prostate cancer showed that co-targeting these factors could revert malignant phenotypes despite underlying genetic alterations." (PMID 41614813, 2025). "Additionally, the protein expression level of CENPF in prostate cancer is high than in normal prostate tissues." (PMID 36937411, 2023). "A former study demonstrated that CENPF silencing alters the metabolic profile of prostate cancer cells and inhibits cell proliferation, suggesting that CENPF may be a key regulator of prostate cancer metabolism." (PMID 36937411, 2023). "On the basis of the previous studies, we discovered that CENPF may play a key role in the progression of prostate cancer." (PMID 36937411, 2023). "The results demonstrated that the overexpressed of the CENPF could promote the ability of proliferation in prostate cancer cells." (PMID 36937411, 2023). "In addition, the Edu staining assay also proved that the proliferation ability of prostate cancer cells was also enhanced with the overexpressed of CENPF." (PMID 36937411, 2023). "In addition, the time-dependent ROC curve also proves the good predictive value of CENPF in prostate cancer." (PMID 36937411, 2023). "In prostate cancer (PC), CENPF has been reported to be a critical regulator of PC metabolism." (PMID 36644760, 2022). "Downregulated CENPF remodels prostate cancer and changes cell metabolism." (PMID 35346060, 2022). "In prostate cancer, CENPF has been shown to predict survival and tumor metastasis." (PMID 33428600, 2021). "Moreover, upregulation of miR-205 has direct inhibitory effects on Centromere Protein F (CENPF) which acts as one of the major oncogenes in prostate cancer and leads to cancer aggressiveness." (PMID 32854238, 2020). "Furthermore, FOXM1 has been observed to drive prostate cancer metastasis or malignancy by forming the COUP–TFII–FOXM1–CENPF cascade or by cooperating with CENPF." (PMID 32629770, 2020). "Increased expression of CENPF in prostate cancer suggests poor prognosis of patients." (PMID 33061942, 2020). "Furthermore, COUP transcription factor 2 (COUP-TFII) promotes metastasis in prostatic cancer (PC) through CENPF signaling." (PMID 31632198, 2019). "Clinical research has demonstrated that high expression levels of CENPF results in poor prognosis in nasopharyngeal carcinoma, colorectal gastrointestinal stromal tumors, esophageal squamous cell carcinoma and prostate cancer." (PMID 30778371, 2019). "Furthermore, our research groups have revealed that CENPF, directly regulated by miR-205-5p, was overexpressed and involved in prostate cancer pathogenesis." (PMID 29928475, 2018). "Therefore, we aim to further explore the role of CENPF in prostate cancer cells." (PMID 36937411, 2023). "The overexpress of CENPF could promote the proliferation ability of prostate cancer cells." (PMID 36937411, 2023). "FOXM1 and CENPF co-expression could be a potential robust prognostic indicator of poor survival and metastasis in prostate cancer, and these two genes may contribute to driving prostate cancer." (PMID 32040444, 2020). "Numerous malignancies, such as including cancer of the prostate, hepatic carcinoma (HCC), and other carcinomas, have been discovered to express CENPF aberrantly." (PMID 39911278, 2025).
prostate carcinoma (continued). "The upregulated gene set included oncogenes such as PIK3CB, FGFRL1, and NCOA2; prostate cancer-related genes such as SPON2, PCAT4, and SCHLAP1; and cell cycle genes such as MKI67, MCM4, KIF4A, CENPF, and FLNB." (PMID 38067373, 2023). "After constructing the prognostic prediction model, SLPI, VSIG2, CENPF, SLC7A1, SMC4, and ITPR2 were finally regarded as the key genes in the prognosis of patients with prostate cancer." (PMID 36937411, 2023). "The time-dependent ROC curve demonstrated that CENPF and TOP2A show good predictive value in prostate cancer patients." (PMID 36937411, 2023). "The abnormal expression of CENPF has been reported in multiple cancers, including prostate cancer, HCC and nasopharyngeal carcinoma, indicating that high CENPF expression is a malignant indicator." (PMID 37108172, 2023). "The aberrant expression of CENPF has been found in multiple malignancies, including hepatocellular carcinoma (HCC), prostate cancer, and other carcinomas, but little literature about ACC." (PMID 35123514, 2022). "Specifically, the latest studies have acclaimed that overexpression of CENPF markedly promoted cell proliferation in HCC and induced tumor metastasis in prostate cancer with a poor prognosis." (PMID 35123514, 2022). "CENPF is related to cellular proliferation and mitotic activity, driving prostate cancer metastasis, while HJURP is involved in regulating the centromeric deposition of CENPF and controls cell cycle progression." (PMID 36245556, 2022). "Some studies have found that CENPF and FOXM1 are major regulators in prostate cancer development; they synergistically promote prostate cancer malignant progression and metastasis." (PMID 35141213, 2021). "Recent studies have shown that CENPF and FOXM1 were important regulators of prostate cancer malignancies and prognostic indicators for poor survival and extensive tumor metastasis." (PMID 33854594, 2021). "It has been reported that chicken ovalbumin upstream promoter-transcription factor 2 (COUP-TFII) promoted metastasis of prostate cancer through signal transduction of FOXM1 and CENPF." (PMID 33428600, 2021). "It was recently shown that CENPF and FOXM1 are synergistic master regulators of prostate cancer malignancy and are prognostic indicators of poor survival and metastasis." (PMID 31632198, 2019). "PCAT-1 is transcribed from chr8q24 and promotes prostate cancer cell proliferation by regulating target genes in trans, including BRCA2 (breast cancer early-onset 2), CENPF (centromere protein F) and CENPE (centromere protein E)." (PMID 23875687, 2013). "In addition, CENPF may be a promising CAF-dependent biomarker for the diagnosis and prognosis of prostate cancer." (PMID 36937411, 2023).
hepatocellular carcinoma (23 papers, 2012 to 2025). A malignant tumor that arises from hepatocytes. "In particular, CENPF overexpression is significantly associated with tumor metastasis and poor prognosis of hepatocellular carcinoma or breast cancer patients." (PMID 37108172, 2023). "In hepatocellular carcinoma, overexpression of CENPF is predictive of acute prognosis and promotes disease progression." (PMID 38536579, 2024). "In the peripheral blood of hepatocellular carcinoma patients, the expression of CENPF was upregulated and was found to be positively correlated with the percentage of CD8+ T cells and negatively correlated with the percentage of CD4+ T cells." (PMID 36644760, 2022). "HELLS overexpression can also promote the growth of hepatocellular carcinoma by activating the transcription of centromere protein F." (PMID 35774795, 2022). "CENPF has been reported to be frequently expressed at high levels in hepatocellular carcinoma, and suppression of CENPF leads to growth inhibition and cell cycle arrest." (PMID 33061942, 2020). "It is worth mentioning that the overexpression of CENPF and CIT, as is the case in this study, has been associated with different types of cancer such as cervical cancer, hepatocellular carcinoma, osteosarcoma, bladder cancer, and esophageal squamous cell carcinoma." (PMID 35831333, 2022). "Furthermore, a down-regulation system of CENPF, siRNA, was constructed to probe the effect of CENPF on the function of hepatoma cells in the cell line of human HepG2 cells." (PMID 33854594, 2021). "CENPF amplification is a frequent event in hepatocellular carcinomas." (PMID 25003081, 2014). "However, in another study of hepatocellular carcinoma, knockdown of CENPF resulted in the accumulation of cells in G2/M phase and S phase, and the reduction of cells in G0/G1 phase, which indicated that CENPF may function differently in different tumors." (PMID 40299364, 2025). "But the molecular mechanism and prognostic value of CENPF in patients with hepatocellular carcinoma (HCC) are still unclear." (PMID 33854594, 2021). "CENPF was identified as a marker of cell proliferation in several human malignancies, including BC and is overexpressed in hepatocellular carcinoma (HCC) and other tumors." (PMID 31632198, 2019). "Lines of evidence implicate CENPF and FOXM1 may have novel co-operative roles in driving hepatocellular carcinoma (HCC)." (PMID 35865168, 2022).
gastric cancer (17 papers, 2015 to 2026). A primary or metastatic malignant neoplasm involving the stomach. "Finally, SGO2, TTK, and CENPF were associated with the acquired chemoresistance to cisplatin and fluorouracil combination chemotherapy in gastric cancer." (PMID 36213825, 2022). "Overexpression of miR-1-3p inhibits the proliferation and invasion of gastric cancer cells by targeting stanniocalcin 2 (STC2) or centromere protein F (CENPF), in which CENPF is also associated with migration." (PMID 37907984, 2023). "The key genes had been validated in GSE14210, and SGO2, TTK, and CENPF have been related with the obtained chemoresistance to cisplatin and fluorouracil mixture chemotherapy in gastric cancer." (PMID 36213825, 2022). "Similarly, miR-1-3p has been shown to inhibit gastric cancer progression by targeting CENPF, and to suppress colorectal cancer cell proliferation and metastasis by targeting YWHAZ and regulating EMT." (PMID 39062049, 2024). "Besides, the HnRNPR-CCNB1/CENPF axis was involved in the proliferation and metastasis of gastric cancer." (PMID 35354488, 2022). "Knockdown of CENPF attenuates the cell growth and invasion of gastric cancer." (PMID 33061942, 2020). "In gastric cancer (GC) and in head and neck squamous cell carcinoma (HNSCC), METTL3 upregulates centromere protein F (CENPF), ensuring an adequate blood supply for rapidly dividing tumor cells." (PMID 39098905, 2024).
lung carcinoma (17 papers, 2019 to 2025). "The ROC curves demonstrated good diagnostic efficacy for lung cancer, with AUC values of 0.962, 0.924, 0.886, and 0.95 for the four hub genes CENPF, AURKA, PBK, and CCNB1, respectively." (PMID 36984548, 2023). "Similarly, high CENPF mRNA expression was associated with decreased survival in lung cancer (HR = 1.57 (1.38–1.78), p = 3.4e−12)." (PMID 31632198, 2019). "CENPF (Centromere protein F) is a gene related to chromosome segregation during mitosis that reduces overall survival in lung cancer and is a hub gene (AURKB, BUB1B, KIF2C, HMMR, CENPF, and CENPU) overexpressed in cancer patients." (PMID 36661515, 2023). "Analysis of four lung cancer gene chips revealed that the nuclear protein gene, human centromere protein F (CENPF), is highly expressed in lung adenocarcinoma (LUAD)." (PMID 33428600, 2021). "Our analysis also demonstrated significantly higher CENPF expression in lung cancer versus normal samples." (PMID 31632198, 2019). "Nonetheless, there has been little research on CENPF’s oncogenic significance in lung cancer." (PMID 36984548, 2023). "Lung cancer patients’ prognoses are often foreseen using matched prognostic models, and genes CENPF, AURKA, PBK, and CCNB1 in lung cancer may serve as therapeutic targets, which require further investigations." (PMID 36984548, 2023). "CENPF was viewed as a prognostic indicator of lung cancer patients with COVID-19 infection." (PMID 36911196, 2023). "CENPF is one of the overexpressed genes that appeared in three of the LC CCPs and formed five different alignments with Gedevo, one of which was in 60% of the possible comparisons, suggesting its importance in lung cancer." (PMID 36661515, 2023). "Additionally, silencing CENPF substantially reduced LUAD cell tumor development in an experimental xenograft lung cancer model using naked mice armpits of the right forelimb." (PMID 35354488, 2022). "Furthermore, AURKB, CCNB2, CDC20, CDCA5, CDCA8, CENPF, and KNTC1 are were highly expressed in lung cancer tissues and were associated with poor prognosis." (PMID 35598017, 2022). "Finally, experimental xenograft lung cancer model of nude mice armpit of right forelimb to determine the effect of CENPF on LUAD tumorigenesis." (PMID 33390818, 2021). "Furthermore, knockdown of CENPF significantly inhibited the tumor growth of the LUAD cells in an experimental xenograft lung cancer model of nude mice armpit of right forelimb." (PMID 33390818, 2021). "Besides, after CENPF knockdown in A549 cells, we performed vitro experiments to evaluate the role of CENPF in colony formation, cell cycle and apoptosis of lung cancer cell lines." (PMID 33390818, 2021). "Finally, we performed an experimental xenograft lung cancer model of nude mice armpit of right forelimb to determine the effect of CENPF on LUAD cells tumorigenesis in vivo." (PMID 33390818, 2021). "First, we examined CENPF expression in lung cancer cell lines." (PMID 33390818, 2021). "As CENPF is highly expressed in BC, particularly in bone metastatic lesions, these results are consistent with its reported role in bone metastasis in prostate and lung cancer cases." (PMID 31632198, 2019). "FOXM1 and CENPF expression is positively correlated with lncRNA SBF2-AS1 expression, and their synergistic interaction promotes the proliferation of lung cancer cells." (PMID 35410446, 2022). "Overall, SH3PXD2A-AS1 can promote the expression of target genes such as FOXM1, CENPF and KIF20A by binding to the DHX9 protein, thereby promoting the cell cycle progression and cell proliferation of NSCLC, and promoting the growth of lung cancer." (PMID 35410446, 2022). "To determine the effect of CENPF on LUAD cells tumorigenesis in vivo, we performed an experimental xenograft lung cancer model of nude mice armpit of right forelimb." (PMID 33390818, 2021).
lung carcinoma (continued). "Similarly, in lung cancer, radioresistance-related signatures also predict patient outcomes and immune status, identifying TOP2A, CDH3, ASPM, CENPF, SLC2A1, and PRC1 as potential detection biomarkers for early lung cancer." (PMID 41041339, 2025). "CENPF also appears in the LCI coexpression network and is one of the genes that has been deregulated in lung cancer but has not been associated with the acquisition of the hallmarks of cancer in this tissue." (PMID 36101460, 2022). "In the datasets reported by Bhattacharjee and coworkers from 186 samples, CENPF was 24.5 fold higher in lung cancer samples compared to normal tissue." (PMID 31632198, 2019). "Among them, five genes (ASPM, CDCA8, CENPF, CEP55, and PLK1) were present in both three hub gene lists (intersection gene, DEGs, and WCGNA module) suggesting that these five genes may become key genes involved in HIV‐infected lung cancer." (PMID 35608130, 2023).